IGHV3-72 (immunoglobulin heavy variable 3-72)
Description:
V region of the variable domain of immunoglobulin heavy chains that participates in the antigen recognition. Immunoglobulins, also known as antibodies, are membrane-bound or secreted glycoproteins produced by B lymphocytes. In the recognition phase of humoral immunity, the membrane-bound immunoglobulins serve as receptors which, upon binding of a specific antigen, trigger the clonal expansion and differentiation of B lymphocytes into immunoglobulins-secreting plasma cells. Secreted immunoglobulins mediate the effector phase of humoral immunity, which results in the elimination of bound antigens. The antigen binding site is formed by the variable domain of one heavy chain, together with that of its associated light chain. Thus, each immunoglobulin has two antigen binding sites with remarkable affinity for a particular antigen. The variable domains are assembled by a process called V-(D)-J rearrangement and can then be subjected to somatic hypermutations which, after exposure to antigen and selection, allow affinity maturation for a particular antigen.
Synonyms: IGHV372; VH
Gene: Immunoglobulin variable (V) gene on chromosome 14 (106,790,694 to 106,791,233, reverse strand). Ensembl gene ENSG00000225698.
Subcellular location: Secreted; Cell membrane
Gene Ontology:
Molecular function: antigen binding
Biological process: immunoglobulin mediated immune response
Cellular component: extracellular region; plasma membrane
Homologues: Orthologues: mouse Ighv7-3 (75% identical), mouse Ighv7-1 (74% identical), mouse Ighv7-4 (70% identical), mouse Ighv7-2 (68% identical). Paralogues in human: IGHV3OR15-7 (89% identical), IGHV3-73 (87% identical), IGHV3-49 (85% identical), IGHV3-15 (82% identical), IGHV3-74 (80% identical), IGHV3-11 (79% identical), IGHV3-66 (79% identical), IGHV3-23 (78% identical), IGHV3-43 (78% identical), IGHV3-48 (78% identical), IGHV3-20 (77% identical), IGHV3-21 (77% identical), and 65 more.